CD4 (CD4 molecule)
Diseases named in the same sentence as CD4 in open-access papers (continued):
Sharing a sentence is not in itself a finding about the gene and the disease.
malaria (continued). "In fact, IL-10– and IFN-γ–coproducing CD4+ T (type I regulatory [Tr1]) cells comprise a substantial fraction of cells responding to parasite antigen stimulation of immune cells from African children living in malaria-endemic areas." (PMID 37781920, 2023). "The polyfunctional of these effector PvDBPII-specific CD4+ T cells could help in malaria protection since it was reported that they increased durability of protection in malaria vaccine clinical studies 29,30." (PMID 37173361, 2023). "P2RX7 acts at the beginning of the malaria immune response, before Th1/Tfh polarization, when activated CD4+ T cells constitute a single population that co-expresses T-bet and Bcl6, and contributes exclusively to the differentiation of Th1 cells, without affecting the generation of early Tfh cells." (PMID 36993971, 2023). "A better understanding of the CD4+ T cell response to malaria in pregnancy could help inform the design of effective vaccines in malaria-endemic settings." (PMID 37634385, 2023). "Type I IFN signaling in CD4+ T cells drives Tr1 cell development in experimental malaria." (PMID 37781920, 2023). "In P. chabaudi malaria, CD4+ T cells proliferate intensely and are metabolically very active around day 4 p.i. and progressively stop dividing and differentiate into effector cells until day 7 p.i., after which most activated cells die in parallel with control of acute parasitemia." (PMID 36993971, 2023). "Studies concerning malaria's impact on the level of CD4+-T cells are still controversial." (PMID 36600836, 2023). "Here we showed that higher baseline frequencies and a subsequent early decrease of malaria-specific IFNγ+CD4+ T cells following PfSPZI DVI, which precedes the first detection of malaria parasite in the blood even by PCR, were associated with control of parasitemia." (PMID 35922467, 2022). "Our results showed that rVSV vaccines containing malaria antigens could induce both CD4+ and CD8+ T cells secreting IFN-γ and IL-2." (PMID 36504817, 2022). "Moreover, IL-10-producing Foxp3+Tbet+CD4+ regulatory T cells are considered an important source of IL-10 during malaria pathogenesis." (PMID 35277125, 2022). "Thus, CTLA‐4 expression remains elevated among memory CD4+ T cells in both human and mouse asymptomatic malaria." (PMID 35475529, 2022). "The sequencing results further implied that PD-1+ CD4 T cells could be more activated and could secrete more cytokines to modulate against malaria immunity." (PMID 36091043, 2022). "Interestingly, IFN-γ and TNF-α producing CD4+ T cells play a crucial role in the protective immune response to the blood-stages of the malaria parasite in humans." (PMID 35812841, 2022). "Overall, for each antigen, we detected significant differences in the number of epitopes that could be used as components of a multiepitope malaria vaccine, with CelTOS and P36 having both CD4+ and CD8+ conserved T-cell epitopes." (PMID 35744609, 2022). "We showed malaria-specific co-inhibitory rich CD4+ T cells to be capable of suppressing the activation of naïve T cells and might regulate the amount of T cell activation in acute malaria." (PMID 35874786, 2022). "Additionally, IFN-γ/IL-10 co-producing cells also have been described as a dominant population of CD4+ T cells in acute malaria infection with malaria parasites." (PMID 35277125, 2022). "Malaria parasites, malaria density and absolute CD4 counts were carried out on all three groups." (PMID 36483323, 2022). "A concurrent decrease in the frequency of both γδ T and CD4+ T cells suggests that these subsets might be part of an immune program that confers protection in tissues that participate in immunity to malaria parasites." (PMID 35922467, 2022). "Reduced vaccine responses may result from the impact that repeated malaria exposure can have on B cells, CD4+ T cells, and innate immune cell phenotypes and functions, which influence antibody generation." (PMID 36002841, 2022).
malaria (continued). "PD-1+ CD4 T cells appeared to be more activated and could secrete more cytokines to regulate the host’s immune responses against malaria." (PMID 36091043, 2022). "In general, cell populations overrepresented in symptomatic malaria were positively correlated with the symptomatic transcriptional signature, with T‐bet+ memory CD4+ T cells and activated IgM+ MBCs featuring the highest number of associations with gene expression profiles (Fig EV3)." (PMID 35475529, 2022). "CD4+ T-helper cells have been reported to be involved in malaria conferring protection." (PMID 33632233, 2021). "Host-directed therapies or immune check point blockade may be one such approach to overcome malaria-driven CD4+ T cell imprinting." (PMID 36845571, 2021). "Indeed, others have suggested that the Th1 and Tfh cells can exist as a continuum, where the balance between Bcl6, STAT3, Blimp-1 and Tbet expression in CD4+ T cells determine the predominant Th subset in effector CD4+ T cells in malaria." (PMID 36845571, 2021). "Malaria studies in mice models have shown that CD4 + T cell intrinsic Bcl6 signalling is required for induction of Tfh responses, and that the cytokines IL-6 and IL-21 are also required whereas the presence of Type 1 IFN tended to compromise Tfh cells and Tfh-mediated GC responses." (PMID 34666102, 2021). "Along with malaria-driven changes to Tfh and CD4+ T cells, other confounding factors may also need consideration in Tfh cell-targeted therapies." (PMID 36845571, 2021). "Although CD8+ and CD4 + T cells have a protective role against the liver stage of malaria, results of earlier depletion and adoptive transfer experiments in mice models seemed to suggest that these cells had a limited role or even no role in protection against blood stages." (PMID 34666102, 2021). "Additionally, Tr27 cells, which are IL-27-producing CD4+ T cells, are induced by the malaria parasite to regulate CD4+ T cell responses against the infection." (PMID 33995336, 2021). "Here, we significantly extend this research by optimizing a blood-stage liposomal vaccine using the P. yoelii rodent malaria model and interrogating the immune response to identify CD4+ T cells, IFN-γ, TNF, and IL-10 as critical mediators of protective immunity." (PMID 34663097, 2021). "Although Bcl6 has been recognized to be the lineage-determining transcription factor for Tfh cells in viral infection as early as 2009, it has only recently been determined that CD4+ T cell-intrinsic Bcl6 signalling is also required for the induction of Tfh responses in malaria." (PMID 36845571, 2021). "During the murine modeling of severe malaria, conventional DCs (cDCs) lose the ability to phagocytose and present parasitic antigens when the burden of pathogen increases resulting in the suppression of CD4+ T cell responses." (PMID 34414129, 2021). "Malaria has been confirmed to deplete CD4+ T cells especially, the memory T cells." (PMID 35223394, 2021). "In 2017, WHO published guidelines recommending cotrimoxazole prophylaxis to reduce morbidity and mortality among PLHIV whose CD4 count was ≤350 cells/mm3 or at clinical stage 3 or 4 or lifelong cotrimoxazole for any CD4 count in settings with a high prevalence of malaria or bacterial infections." (PMID 34006230, 2021). "Similarly, vaccination of rhesus macaques with anti-DEC205-tagged antigen of malaria circumsporozoite also elicited CD4+ T cell-biased responses even with the use of poly(I:C) as an adjuvant." (PMID 34125864, 2021). "The cytokines generally produced by CD4+ T cells may influence other immune cells involved in response to malaria and development of immunity." (PMID 32981095, 2021). "Yet during severe malaria, a strong Th1-polarizing environment promotes the development of dysfunctional T-bet+ “Th1-like” CD4+ Tfh cells, which exhibit poor help activity on B cell responses and lead to B cell apoptosis or differentiation into short-lived plasma cells and atypical memory B cells." (PMID 32265335, 2020).
malaria (continued). "Whilst interleukin 4 (IL4) production by T helper 2 (Th2) T cells can support antibody production by B cells, IFNγ production by γδ T cells and T helper 1 (Th1) CD4+ T cells has been suggested to also play a role in mediating blood-stage protection in rodent malaria models." (PMID 33153189, 2020). "In the 2014 Malawi national health facility survey to assess access to diagnostic tests, 82% of hospitals had access to hemoglobin testing, with access only superseded by malaria diagnostic testing (95%) and HIV diagnostic testing (95%), whereas CD4 testing was only available in 43% of hospitals." (PMID 33161899, 2020). "In our study, CD4hiCD38hi cells were increased in proportion to malaria disease severity, and there are phenotypic analogies between the CD4hiCD38hi T cells identified herein and IL‐10‐expressing CD4+ T cells that were shown to limit immunopathology in a rodent malaria model." (PMID 33282291, 2020). "Thus, the regulation of inflammatory responses, orchestrated by CD4 + T cells and monocytes/macrophages, is key to the successful resolution of malaria blood-stage infection." (PMID 33036624, 2020). "The main thrust of research groups developing vaccines against the P. falciparum malaria Spz stage has involved Spz recombinant proteins, DNA or viral vectored protein fragments and attenuated Spz vaccines to induce malaria reactive CD4+ and CD8+ T-lymphocyte counts and high antibody (Abs) titres." (PMID 32013956, 2020). "Vaccines against blood-stage malaria often aim to induce antibodies to neutralize parasite entry into red blood cells, interferon gamma (IFNγ) produced by T helper 1 (Th1) CD4+ T cells or interleukin 4 (IL-4) produced by T helper 2 (Th2) cells to provide B cell help." (PMID 33153189, 2020). "This pattern of reduced expression of IFNG mRNA in the convalescent samples mirrors our previously published observations for CD4+CD38high cells from healthy volunteers (malaria‐naïve Australian volunteers) and for CD4+CD38high cells from CHMI volunteers at day 7 of infection." (PMID 33282291, 2020). "The independent risk factors for placenta malaria include CD4 count at booking less than 350 and patients not treated for symptomatic malaria in pregnancy." (PMID 32103782, 2020). "Similarly, TGFβ was reported to play a protective role against severe malaria in mice, and TGFβ can drive IL-10 production by several different CD4+ T cell subsets, including Treg, Th17 and other FoxP3-negative cells." (PMID 30809232, 2019). "Importantly, a large percentage of malaria antigen-specific CD4+ and CD8+ T cells produced both TNF-α and IFN-γ (with or without MIP-1β), with the remainder generating individual cytokines including IL-2." (PMID 30673723, 2019). "Hence, a better understanding about the development of CD4+ T cell responses during malaria is needed to improve strategies aimed at improving anti-parasitic immunity." (PMID 30809232, 2019). "Evidence from immunological studies following immunisation with malaria and rabies vaccines have revealed the important role of NK cells in protection from vaccine-preventable diseases through their activation by antigen-specific CD4+ T cell-derived IL-244,45." (PMID 30890730, 2019). "In addition to CD4+ Th1 and Tfh cells, Foxp3+ Tregs play an important regulatory role during malaria as a counterbalance to control excessive pro-inflammatory responses and limit immunopathology." (PMID 30915078, 2019). "TB reduces CD4 and CD8 counts and the CD4:CD8 ratio independently of malaria." (PMID 31428162, 2019). "Moreover, infected animals exhibited increased frequencies of circulating α4β7+ CD4 T cells, suggesting that malaria-induced systemic inflammation was enhancing the mucosal homing of activated immune cells." (PMID 31798936, 2019). "Notably, they all had a low baseline CD4 cell count with a relatively higher malaria parasite load compared to the rest of the participants." (PMID 31429785, 2019).
malaria (continued). "Furthermore, the significance of the observation of increased CXCR3 expression on splenic CD4+ T cells during malaria was unclear." (PMID 30915078, 2019). "Altogether, our findings indicate that CXCR3 expression on effector CD4+T-bet+Foxp3− cells may contribute to the migration of these cells to the spleen during malaria suggesting a role for CXCR3 in immunity to P. chabaudi AS infection." (PMID 30915078, 2019). "Severe malaria in coinfected animals might result from impaired humoral immunity and CD4+ T cell responses against parasites." (PMID 31718574, 2019). "However, the higher frequency of GrzB+ CD4+ T cells in children with mild malaria argues against purely kinetic reasons for the differential expression pattern of inhibitory molecules in both groups." (PMID 29555909, 2018). "We have to run blood smear and malaria parasites tests and at the same time do CD4 tests." (PMID 30185191, 2018). "Therefore, we have described a previously unrecognized molecular pathway in regulating CD4+ T cell-mediated protective immunity to blood-stage malaria, and provided an insight into the involvement of neddylation in host resistance to infectious diseases." (PMID 30462731, 2018). "T helper cells (CD4+) are essential to protection from malaria, but it is unknown what kinds of T cells would be both protective and long-lasting." (PMID 29630679, 2018). "We evaluated the performance of a malaria rapid diagnostic test (MRDT) against blood smear microscopy (BSM) among HIV-positive patients in relation to anti-retroviral treatment (ART) status, CD4+ count, fever, cotrimoxazole prophylaxis and malaria density count." (PMID 30568892, 2018). "However, the molecular pathways that directly regulate CD4+ T cell activities or the interplay with B cells during malaria remain elusive." (PMID 30462731, 2018). "The mode of protection remains unclear and a potential immunoregulatory role of GrzB+ CD4+ T cell subsets has been discussed in malaria and other infections." (PMID 29555909, 2018). "Furthermore, T cell intrinsic BACH2 was needed for efficient expansion of CD4+ T cells during experimental malaria in this immunological setting." (PMID 30459773, 2018). "An increase of GrzB+ CD4+ T cells has been repeatedly observed in malaria." (PMID 29555909, 2018). "In the field, certain CSP-specific CD4+ T-cell populations may have been acquired by natural exposure to malaria before and during the entire period of the trial, and may have also been boosted by vaccination." (PMID 28934066, 2018). "The severity of malaria (defined by WHO 2014) was inversely related to CD4 T‐cell count." (PMID 30362663, 2018). "In conclusion, our study results support the hypothesis that the quality of the CD4+ T cell response is an important factor influencing the clinical outcome of malaria." (PMID 29555909, 2018). "Children with complicated versus uncomplicated malaria expressed different CD4+ T cell signatures." (PMID 29555909, 2018). "In addition, children with symptomatic malaria had a higher level of the CD4+CD69+ T cells than the controls (P = 0.0068)." (PMID 30005684, 2018). "Similarly, the expression of PD-1 on CD4+ T cells was more frequently observed in children with acute malaria and there was a trend towards a higher proportion of PD-1+CD4+ T cells in children with complicated than uncomplicated malaria." (PMID 29555909, 2018). "In this study, we investigated using the blood-stage Plasmodium chabaudi (Pc) murine infection model whether P2X7 signaling contributes to CD4 T cell subset differentiation in malaria." (PMID 28859168, 2017). "This underscores the importance of memory CD4+ T-cells in malaria immunity." (PMID 28426727, 2017). "In the few published studies which have used multicolor flow cytometry to assess Pf-specific cytokine production by CD4 T cells at an individual cell level, it has been shown that the Pf-specific CD4 T-cell response in highly malaria-exposed children is dominated by IFNγ and IL10 coproducing cells." (PMID 29097996, 2017).
malaria (continued). "However, we found that the frequency of ICOS expressing cells was significantly increased in the memory, activated memory and total CD4+ T lymphocyte compartments in malaria patients BT." (PMID 28700710, 2017). "This suggest that HIV-infected non-immune adults are at increased risk of severe malaria and the risk is associated with a low CD4 cell counts." (PMID 28346490, 2017). "We measured Pf-specific IFNγ-, IL10-, and TNFα-producing CD4 T-cell responses by multi-parametric flow cytometry in 265 children aged 6 months to 10 years enrolled in a longitudinal observational cohort in a high malaria transmission site in Uganda." (PMID 29097996, 2017). "Human CD4 T cells express P2X7 receptor and secrete IL-2 following eATP stimulation, but it is still unknown whether P2X7 signaling influences the CD4 T cell response in malaria patients." (PMID 28859168, 2017). "Together, these data suggest that a final switch from IFNγ to IL10 production among malaria-specific CD4+ T cells may play a role for in mediating tolerance to malaria." (PMID 29097996, 2017). "To examine how production of these cytokines by Pf-specific CD4 T cells changes with age, we compared children in three age strata (0–3, >3–7, and >7–11 years) spanning the age range during which clinical immunity to malaria typically emerges." (PMID 29097996, 2017). "CD4 T-cell responses may also be important in mediating protection from malaria by preventing parasite infection or restricting parasite replication once infection is established." (PMID 29097996, 2017). "However, many aspects of the Pf-specific CD4 T-cell response in naturally exposed individuals, including the critical effector functions responsible for preventing infection and clinical malaria, remain poorly understood." (PMID 29097996, 2017). "CD4+ T cells play an important role in controlling blood-stage malaria." (PMID 28203236, 2017). "Between 1 February 2012 and 30 September 2013, we conducted an unblinded non-inferiority randomized controlled trial of CTX prophylaxis cessation versus continuation among HIV-1-infected adults on ART for ≥18 mo with CD4 count > 350 cells/mm3 in a malaria-endemic region in Kenya." (PMID 26731191, 2016). "In this context, a role for Foxp3+ CD4+ regulatory T cells (Tregs) as well as non-Foxp3+ activated/memory (CD45RO+) CD4+ T cells in regulating malaria-induced inflammation and subsequent immunopathology is supported by many studies in human patients and in surrogate mouse models." (PMID 27792766, 2016). "Notably, a recent study identified that frequencies of IFN-γ and IL-10 co-producing CD4 T cells were increased in Ugandan children who presented with >2 malaria episodes/year, compared to children who presented with <2 malaria episodes/year." (PMID 27732671, 2016). "High numbers of CD4+ T cells in the peripheral blood of malaria patients expressed CTLA4 and PD1." (PMID 27802341, 2016). "Among the mechanisms described to clear blood-stage Malaria parasites are mature isotypes antibodies and antibody-independent T cell mechanisms, but all of them require the activation of CD4+ T cells." (PMID 27446022, 2016). "We previously reported that recent malaria exposure can dampen subsequent P. falciparum-induced inflammation via a regulatory state mediated in part by the anti-inflammatory cytokine IL-10 produced by CD4+CD25+Foxp3- T cells that also produce IFNγ and TNF5." (PMID 27506615, 2016). "Because tetramers do not exist for tracking parasite-specific CD4+ T cell responses during P. yoelii NL infection, we used CD11a and CD49d as proxy markers for activated Ag-experienced cells, which include malaria-specific effector and memory CD4+ T cell populations." (PMID 27630165, 2016). "Additional studies will be needed in order to validate these findings, and to determine whether the activated CD4 T cells described here represent malaria-specific responses." (PMID 27717402, 2016).